HDAC9 (histone deacetylase 9)
Diseases named in the same sentence as HDAC9 in open-access papers (continued):
Sharing a sentence is not in itself a finding about the gene and the disease.
tumor (continued). "The xenograft experiment revealed that the ability of tumor formation of TAZ-overexpressed HDAC9-knockdown U87 cells in vivo was also rescued." (PMID 25760078, 2015). "Furthermore, the heightened expression of HDAC9 in HNC drives tumor progression, metastasis, and resistance to cisplatin therapy, highlighting its potential as a therapeutic target across various HNC subtypes." (PMID 39628997, 2024). "In addition, the downregulation of HDAC9 decreased the tumor spheroid forming potential of AGSR cells." (PMID 38920983, 2024). "HDAC9 was also closely related to various immunological characteristics [including tumor-infiltrating lymphocytes (TILs), immunosuppressive cytokines, immune-activating cytokines, and major histocompatibility complex (MHC) molecules, all figures were downloaded directly from the TISIDB.]." (PMID 35239708, 2022). "Their results further confirmed increased HDAC9 expression in basal tumor cells." (PMID 34318404, 2021). "In these experiments, HDAC9 counteracted the tumor‐suppressive actions of miR‐936 in Rb cells." (PMID 34318404, 2021). "HDAC9 also inhibited Rb tumor growth in a mouse xenograft model." (PMID 34318404, 2021). "Although the findings reviewed in this section broadly suggest that HDAC9 has pro-oncogenic activity, they also show that HDAC9 may behave differently depending on the tissue context and tumor type." (PMID 34318404, 2021). "HDAC9 may also acts as a tumor suppressor in pancreatic cancer, even though this activity has not been specifically demonstrated." (PMID 34318404, 2021). "HDAC9 may also be able to regulate anti-tumor immune responses by decreasing CD8+ DC and T cell infiltration into the tumor microenvironment." (PMID 34318404, 2021). "Analysis of other signaling pathways that induce dedifferentiation and malignant phenotype via HDAC9 may help us to understand the essential role of HDAC9 in tumor dedifferentiation." (PMID 32977608, 2020). "Likewise, in vivo experiments in mice carrying MDA-MB-231 xenograft tumors with knocked-out HDAC9 exhibited significantly reduced tumor volumes post-paclitaxel treatment, compared to tumor-bearing mice with control sgRNA." (PMID 33042272, 2020). "Abnormally high HDAC9 expression is closely related to proliferation, invasion, and metastasis of various tumor types, and it may up-regulate genes that participate in the oncogenic Ras, VEGF, MAPK, and EGFR signaling pathways." (PMID 33552961, 2020). "Indeed, HDAC9 expression was positively correlated with genes overexpressed in endocrine therapy‐resistant tumor samples, and had a prognostic significance (shorter overall survival with high HDAC9 expression) only in patients who received OHTam." (PMID 31099456, 2019). "Immunohistochemical staining of serial sections of tumor tissues showed that Ki-67 and HDAC9 were expressed in a similar manner, suggesting that HDAC9 may be a proliferation marker." (PMID 31451695, 2019). "Of 2,972 TUs, DE analysis retrieved 127 of Class 1 TUs significantly up-regulated in tumor specimens (adjusted P-value below 0.01, DESeq), including multiple intergenic transcripts and transcripts antisense to protein-coding genes, such as HDAC9, TPO, and FBXL7." (PMID 31732695, 2019). "Interestingly, we observed increased staining for Hdac9 in the cytoplasm and nuclei in this tumor compared to normal urothelium." (PMID 31137849, 2019). "Moreover, HDAC9 siRNA suppressed GC tumor growth and enhanced the antitumor efficacy of cisplatin in GC treatment by inhibiting the proliferation and inducing the apoptosis of GC cells in vitro and in vivo." (PMID 31451695, 2019). "Knockdown HDAC9 decreased proliferation in vitro and tumor formation in vivo." (PMID 25760078, 2015). "Druggability assessments identified HDAC9 as a target for approved drugs potentially repurposed for VC, while PheWAS results suggested a predicted lack of severe genetic pleiotropy for most candidates, with the notable exception of CDKN2A, which showed associations with neoplasms." (PMID 42221083, 2026).
tumor (continued). "Additionally, histone acetylation is widely modulated in TAMs: tumor TAMs often have low expression of class II HDACs (e.g., HDAC9, HDAC10), leading to hyperacetylation and activation of genes that paradoxically encourage macrophages to be trophic rather than toxic to tumors." (PMID 40358164, 2025). "For example, the histone deacetylase 9 (HDAC9) gene that displays lower relative expression in infected cells was also expressed at a reduced level in TashAT2 transfected BoMac lines, as was the gene encoding synaptopodin 2 (SYNPO2), which induces focal adhesion and can act as a tumour suppressor." (PMID 37276213, 2023). "HDAC9 interacts with a variety of transcriptional repressors and oncogenes and may influence anticancer immune responses by limiting T-cell infiltration into the tumor microenvironment (TME)." (PMID 37705968, 2023). "An exhaustive analysis of HDAC9 and immunology via the tumor and immune system interaction database (TISIDB) was performed, and an immune prognostic risk signature was developed based on genes enriched in the top five immune-related pathways under high HDAC9 status." (PMID 35239708, 2022). "However, the roles of HDAC9 in tumor metastasis and EMT remain poorly characterized." (PMID 35203583, 2022). "Even though the status of neither DNMT3b nor HDAC9 has association with PD-L1 levels in our cohort, their inhibitors might upregulate expression of immunostimulatory signals in tumor cells." (PMID 35226658, 2022). "Furthermore, we found that miR-383-5p might serve as a tumor suppressor regulator of gastric tumorigenesis via post-transcriptional repression of HDAC9." (PMID 31365693, 2019). "The results showed that ZNF439 and KDM5D were highly expressed in normal tissues, whereas KMO, FT57, HDAC9, GSAP, and CCR7 were highly expressed in tumor tissues." (PMID 40145017, 2025). "Analysis of the expression of the TILB-related signature genes in B Plasma cells showed that KMO, IFT57, HDAC9, GSAP, and CCR7 were significantly highly expressed in tumor tissue, while ZNF439 and KDM5D showed a similar trend." (PMID 40145017, 2025). "Using qRT-PCR, we confirmed that SATB2, HDAC9, NAP1L2 expression was down-regulated in the tumor group." (PMID 38212708, 2024). "Increases in HDAC activity, as our ATAC-seq data suggest for HDAC5 and HDAC9 in JMML spleen HSPCs, have been identified in a variety of tumor types." (PMID 37958378, 2023). "MeRIP-qPCR results showed that the relative level of m6A modification in HDAC9, MINDY4B was significantly increased in ALV-J induced tumor livers, while the relative level of m6A modification of SOX7 in ALV-J induced tumor livers was significantly decreased." (PMID 35529873, 2022). "HDAC9 inhibition decreases the invasiveness of TNBC cells and effectively blocks tumor angiogenesis in vivo." (PMID 34318404, 2021). "Hdac9-/- mice show decreased antitumor immunity in syngeneic models, as a consequence of decreased CD8+ dendritic cell tumor infiltration and, probably, the increased Foxp3+ infiltration." (PMID 33513699, 2021). "HDAC9 can promotes GBM proliferation and tumor formation by activating the transcription coactivator with PDZ-binding motif (TAZ), an oncogene and an essential downstream effector of the Hippo pathway." (PMID 32682428, 2020). "To further evaluate HDAC9 expression in clinical samples, we examined HDAC9 protein expression in GC samples by IHC in a TMA containing 15 paired GC tumor tissues and paratumor normal tissues." (PMID 31451695, 2019). "HDAC9 has an oncogenic role in OSCC, increasing tumor growth by targeting pro-apoptotic genes, and its overexpression was correlated with reduced overall survival." (PMID 28704968, 2017).
tumor (continued). "HDAC9 promotes GBM proliferation and tumor formation via activation of the transcription coactivator with PDZ-binding motif (TAZ)-mediated EGFR pathway." (PMID 28099914, 2017). "Other genes such as HR23B have been identified as biomarkers for tumor sensitivity to HDI-based therapy and the putative link of these genes with HDAC9 expression remains to be elucidated." (PMID 26930713, 2016). "Furthermore, with the exception of HDAC9, the majority of HDAC family genes were substantially elevated in tumor tissues when comparing mRNA expression in LIHC tissues to normal tissues." (PMID 39512688, 2024). "Regarding class-IIa HDACs, HDAC4 may exhibit either a tumor suppressive or oncogenic role whereas HDAC5 and HDAC9 play a significant role in medulloblastomas." (PMID 37373187, 2023). "HDAC9 was not differentially expressed in LUAD tumor tissues versus normal tissues; however, Kaplan−Meier analysis suggested that its overexpression was associated with better prognosis." (PMID 36072664, 2022). "However, there is quite a consensus in the literature that HDAC4, HDAC7, HDAC9, SIRT2, and SIRT7 are upregulated in GC and seem to be pro-tumor factors, whereas SIRT4, SIRT5, and SIRT6, which are downregulated, seem to have a tumor suppressor function." (PMID 36358890, 2022). "RT-qPCR analysis revealed that the lncRNA levels of HDAC9, CMPK2, MINDY4B were up-regulated in the ALV-J induced tumor livers (positive group) compared to the normal livers in the negative group, whereas lncRNA levels of ATOH8 and LOC100859478 were down-regulated in the positive group." (PMID 35529873, 2022). "HDAC9 overexpression, therefore, appears to be relatively specific for BRM-negative tumor cells." (PMID 34318404, 2021). "HDAC9 may, therefore, contribute to TNBC invasiveness and tumor angiogenesis by suppressing miR-206 expression." (PMID 34318404, 2021). "Although not clearly defined until now, a tumor suppressor function for HDAC9 cannot be excluded." (PMID 33513699, 2021). "Among the rest of HDACs, studied in oral cancer, HDAC-6, HDAC-8 and HDAC-9 revealed to be upregulated in oral SCC, without demonstrating any interaction with clinicopathological parameters, other than tumor aggressiveness in the case of HDAC-6." (PMID 34441281, 2021).
infection (75 papers, 2008 to 2025). The state of being infected such as from the introduction of a foreign agent such as serum, vaccine, antigenic substance or organism. "However, compared with the other two groups, the group with a MOI of 10 exhibited the highest HDAC9 mRNA expression and highest infection efficiency." (PMID 39021502, 2024). "After infection with FMDV, the expression of viral RNA and protein, viral titers, and the copies of viral RNA in HDAC9-KO cells were significantly higher than those in NC cells." (PMID 35250927, 2022). "Expression of several histone deacetylases was also regulated during infection: HDAC2 and HDAC10 expression levels increased, while HDAC3, HDAC6, and HDAC9 expression decreased." (PMID 18331636, 2008). "Thus, we found significant interactions of diet and infection for several genes, especially those related to the mucosal barrier, such as DCLK1, HDAC9, IL13RA1, MUC2 and HDAC1 (Fold change 2.5, 1.9, 1.3, 1.3 and − 1.2, respectively)." (PMID 38081984, 2023). "Interestingly, upon infection, the interaction of MEF-2A with HDAC9 was expectedly diminished since HDAC9 binds to the C-terminal TAD domain of MEF-2 to repress its transcriptional activity." (PMID 25809782, 2015).
cardiovascular diseases (38 papers, 2012 to 2025). "The data presented here indicate a novel VSMC-specific function for HDAC9 from those previously implicated in cardiovascular disease." (PMID 29520069, 2018). "IL-1β up-regulated HDAC9; HDACs (histone deacetylases) are involved in atherogenesis and HDAC-inhibitors are a potential therapeutic target for cardiovascular disease." (PMID 28323859, 2017). "Moreover, HDAC9 plays important roles in maintaining vascular smooth muscle and endothelial cell function, with its inhibition showing therapeutic potential in cardiovascular diseases." (PMID 41257548, 2025). "Nevertheless, more extensive investigations will be required to determine whether overexpression of Hdac9 promotes cardiovascular disease under different experimental conditions." (PMID 38672510, 2024). "In a community sample of >330,000 adults, we found confirmatory evidence in support of HDAC9 as a key regulator and potential therapeutic target for VSMC-driven cardiovascular disease, with suggestive evidence of a reverse effect on kidney disease." (PMID 32585591, 2020). "Analysis of the interactome and disease-related network on the 44-dysregulated genes identified HDAC9, SMAD4, PTGFR, and PRKCE as the highest scoring genes within the cardiovascular disease category." (PMID 29520069, 2018). "We predicted 6 candidate genes (PANK1, TRIB1, BMPR2, HDAC9, THBS1, and LARP1) that might bind to miR-942-5p and played a role in cardiovascular disease." (PMID 33869307, 2021).
metabolic disorders (29 papers, 2012 to 2025). "It is possible that PA induced HDAC9 is regulated by related enhancer SNPs to modulate macrophage functions associated with inflammation in metabolic disorders." (PMID 40068774, 2025). "Next, we investigated the role of liver HDAC9 in the process by which acetate regulates metabolic disorders." (PMID 39741391, 2025). "Here, we investigated the effect of adipocyte-specific HDAC9 gene knockout (A-KO) on adipose tissue function and metabolic disease in the setting of DIO." (PMID 36078104, 2022). "Metabolic disorders might lead to changes in HDAC9 expression and activity, or metabolism and HDAC9 could both be regulated by the same upstream signal; this will require rigorous biological experiments to verify." (PMID 35239708, 2022). "In other words, changes in HDAC9, a regulator of protein posttranslational modifications, could potentially be connected to metabolic disorders." (PMID 35239708, 2022). "Thus, a dynamic interplay between HDAC9 expressing cells within the SVF and adipocytes may contribute to the development of adipose tissue dysfunction and metabolic disease." (PMID 36078104, 2022). "In conclusion, our findings suggest that HDAC9 expressed in mature adipocytes during DIO plays an important role in regulating adipose tissue function and metabolic disease in female, but not male, mice." (PMID 36078104, 2022).
psychiatric disorder (16 papers, 2012 to 2025). A disorder characterized by behavioral and/or psychological abnormalities, often accompanied by physical symptoms. "Copy number variation in HDAC9 gene is thought to be associated with the etiology of some psychiatric disorders." (PMID 37690046, 2023).
brain diseases (12 papers, 2013 to 2023). "However, the role of HDAC9-driven deacetylase activity in the context of brain diseases is not well understood, let alone in neuropathic pain regulation." (PMID 37945654, 2023).
HDAC9 also shares sentences with these, for which no sentence is quoted: colon carcinoma (124 papers); hematological malignancies (110); neurodegenerative disease (88); neuroblastoma (85); T-cell lymphoma (73); acute myeloid leukemia (69); Alzheimer disease (60); epilepsy (44); neurological disorders (43); peripheral T-cell lymphoma (42); sarcoma (38); triple-negative breast carcinoma (38); thyroid cancer (37); Huntington disease (35); Anxiety (32); Parkinson disease (32); Thrombocytopenia (28); hematological cancers (24); myelodysplastic syndrome (22); uveal melanoma (22); diffuse large B-cell lymphoma (21); Arthritis (20); rheumatoid arthritis (20); bipolar disorder (19); squamous cell carcinoma (18); amyotrophic lateral sclerosis (17); kidney disease (17); chronic obstructive pulmonary disease (16); renal cell carcinoma (16); synovial sarcoma (16).
A further 503 diseases each share a sentence with HDAC9 in 15 papers or fewer.